PIP5KL1 (phosphatidylinositol-4-phosphate 5-kinase like 1)
Description:
Likely functions as a regulatory or scaffold-like protein that modulates the subcellular localization and activity of type I PI(4)P 5-kinases (PIPKs) (By similarity). Lacks intrinsic lipid kinase activity (By similarity).
Synonyms: bA203J24.5; MGC46424; PIPKH
Tractability: Antibody: its Gene Ontology location is reachable by antibodies, with medium confidence.
Gene: Protein-coding gene on chromosome 9 (127,920,881 to 127,930,785, reverse strand). Ensembl gene ENSG00000167103.
Subcellular location: Cytoplasm; Membrane
Subcellular location (Human Protein Atlas): Cytosol
Gene Ontology:
Molecular function: 1-phosphatidylinositol-4-phosphate 5-kinase activity; phosphatidylinositol kinase activity
Biological process: negative regulation of cell migration; negative regulation of mitochondrial membrane potential; negative regulation of phosphatidylinositol 3-kinase/protein kinase B signal transduction; positive regulation of apoptotic process; phosphatidylinositol phosphate biosynthetic process; phosphatidylinositol metabolic process; regulation of signal transduction
Cellular component: cytosol; cytoplasm; membrane
Genetic constraint (gnomAD): Loss-of-function variants: 44 observed, 32.69 expected, observed/expected ratio (o/e) 1.35, 90% interval 1.06 to 1.72. The synonymous counts are far from expectation, so gnomAD's model fits this gene poorly and the ratio says little. Missense variants: 575 observed, 444.19 expected, observed/expected ratio (o/e) 1.29, 90% interval 1.21 to 1.39. Synonymous variants: 255 observed, 186.36 expected, observed/expected ratio (o/e) 1.37, 90% interval 1.24 to 1.52.
Homologues: Orthologues: chimpanzee PIP5KL1 (99% identical), macaque PIP5KL1 (97% identical), dog PIP5KL1 (92% identical), pig PIP5KL1 (90% identical), rabbit PIP5KL1 (87% identical), guinea pig PIP5KL1 (86% identical), rat Pip5kl1 (74% identical), mouse Pip5kl1 (73% identical), zebrafish pip5kl1 (56% identical), tropical clawed frog pip5kl1 (53% identical). Paralogues in human: PIP5K1A (25% identical), PIP5K1C (25% identical), PIP5K1B (23% identical), PIP4K2A (23% identical), PIP4K2C (22% identical), PIP4K2B (21% identical).
Diseases named in the same sentence as PIP5KL1 in open-access papers:
PIP5KL1 is named in the same sentence as 2 diseases in open-access papers, as found by Europe PMC text mining. Sharing a sentence is not in itself a finding about the gene and the disease. The quoted sentences say what the papers report.
tumor (1 paper, 2019). "PIP5KL1 upregulation suppresses tumor cell proliferation, migration, and growth." (PMID 31024232, 2019).
PIP5KL1 also shares sentences with these, for which no sentence is quoted: gastric cancer (1 paper).